ALK (ALK receptor tyrosine kinase)
Diseases named in the same sentence as ALK in open-access papers (continued):
Sharing a sentence is not in itself a finding about the gene and the disease.
non-small cell lung carcinoma (continued). "ALK fusion proteins have been found be critical oncogenic drivers in some cancers, such as non-small cell lung cancer (NSCLC), ALCL, and inflammatory myofibroblastic tumor (IMT)." (PMID 30400214, 2018). "Resistance to ALK inhibitors has also become a critical issue in the treatment of non-small cell lung carcinoma (NSCLC) bearing the ALK-fusion gene." (PMID 29760954, 2018). "Non-small cell lung carcinoma (NSCLC) harboring rearrangements of the anaplastic lymphoma kinase (ALK) gene and the ROS1 oncogene constitute a unique molecular subgroup of this patient population." (PMID 29774128, 2018). "In a study, Rizzo and colleagues investigated the association between conventional CT features and EGFR, ALK, KRAS mutations in non-small cell lung cancer." (PMID 30547844, 2018). "Crizotinib is an effective drug for patients with anaplastic lymphoma kinase (ALK)-positive non-small-cell lung cancer (NSCLC), but upon treatment, the tumors inevitably become crizotinib resistant in time." (PMID 29300322, 2018). "Human non-small cell lung cancer (NSCLC) cell lines harboring wild-type ALK (A549), EML4-ALK translocation (H3122) and murine Lewis Lung Cancer (LLC) cells were investigated." (PMID 29304828, 2018). "Alterations (paracentric inversion/translocation) of the anaplastic lymphoma kinase (ALK) gene occur in about 3–4% of non-small cell lung cancers (NSCLC) and represent a drugable target." (PMID 30466405, 2018). "Targeted anti-ALK therapy has been shown to elicit good responses and dramatically prolong overall survival (OS) in patients with non-small cell lung cancer (NSCLC) harboring ALK rearrangement." (PMID 29844868, 2018). "The anaplastic lymphoma kinase (ALK) fusion gene is found in about 3-5% of patients with non-small cell lung cancer (NSCLC)." (PMID 29930762, 2018). "Here, we also showed a case of ALK-positive non-small cell lung cancer with multiple renal cysts that developed during crizotinib administration." (PMID 30257437, 2018). "Therapeutic strategies for non-small cell lung cancer are based on mutation of epidermal growth factor receptor (EGFR), Kirsten murine sarcoma virus (KRAS), or Anaplastic lymphoma kinase (ALK)." (PMID 29360794, 2018). "Rearrangement in the anaplastic lymphoma kinase (ALK) gene is one of the oncogenic drivers in non-small cell lung cancer (NSCLC) patients." (PMID 29632648, 2018). "When activated in cancer it represents a target for specific inhibitors, such as crizotinib, ceritinib, alectinib etc. which use has demonstrated significant effectiveness in ALK-positive patients, in particular ALK-positive non- small cell lung cancer." (PMID 29455642, 2018). "Other than ALCL, ALK genetic alterations were identified in a variety of tumors including neuroblastoma (NB), myofibroblastoma and non-small cell lung cancer (NSCLC)." (PMID 29535836, 2018). "The presence of anti-ALK antibodies was also observed in ALCL patients with variant ALK fusion partners, ALK-positive diffuse large B cell lymphoma, and in ALK-positive non-small cell lung carcinoma (NSCLC)." (PMID 29642597, 2018). "The development of ALK inhibitors following the identification of the EML4-ALK fusion gene in Non-Small Cell Lung Cancer (NSCLC) has opened new possibilities for ALK-positive ALCL." (PMID 29601554, 2018). "Anaplastic lymphoma kinase (ALK) is considered as a validated molecular target in multiple malignancies, such as non-small cell lung cancer (NSCLC)." (PMID 30006516, 2018). "The objective of this study was to explore the efficacy of crizotinib in advanced non-small-cell lung cancer (NSCLC) with concomitant ALK rearrangement and c-Met overexpression." (PMID 30477470, 2018). "Anaplastic lymphoma kinase (ALK) rearrangement occurs in approximately 2–7% of patients with non-small cell lung cancer (NSCLC)." (PMID 30340555, 2018).
non-small cell lung carcinoma (continued). "Similar paradigms of second- and third-generation kinase inhibitors to tackle drug resistance mutations arising from first-generation inhibitors are also found in mutant EGFR and ALK-fusion positive non-small-cell lung cancer (NSCLC)." (PMID 30072489, 2018). "Rearrangement of the anaplastic lymphoma kinase (ALK) gene occurs in approximately 5% of patients with advanced non-small-cell lung cancer (ALK-positive NSCLC)." (PMID 29748847, 2018). "In 2007, anaplastic lymphoma kinase (ALK) was discovered as a potential target in non-small cell lung cancer (NSCLC)." (PMID 30453899, 2018). "In non-small cell lung cancer, FDG-PET uptake and CT-ground-glass-opacity features were associated with treatment-informing traits including EGFR-mutations and ALK-rearrangements." (PMID 29732009, 2018). "In the year 2011, four kinase inhibitors, vemurafenib, vandetanib, ruxolitinib, and crizotinib were approved for the treatment of melanoma, thyroid cancer, myelofibrosis and ALK-positive non-small cell lung cancer." (PMID 29455673, 2018). "Several of these small molecule ALK inhibitors have recently gone into phase 1 clinical trials for patients with refractory neuroblastoma, inflammatory myofibroblastic tumour, non-small-cell lung cancer (NSCLC) and anaplastic large-cell lymphoma (ALCL)." (PMID 29290991, 2017). "ALK positive non-small cell lung cancer is highly responsive to ALK inhibitors such as crizotinib, but drug resistance typically develops within a year of treatment." (PMID 29066738, 2017). "Lorlatinib—a ROS1/ALK inhibitor—is currently undergoing clinical trials for the treatment of non-small cell lung cancers." (PMID 28594000, 2017). "The practical feasibility of combination ALK/IGF-1R inhibition as a clinical strategy has been given a boost by recent research into the IGF-1R inhibitor AXL1717 in advanced non-small cell lung cancer." (PMID 29066738, 2017). "Its efficacy and tolerability in cancer therapy was first demonstrated in ALK-positive non-small cell lung cancer (NSCLC), ultimately leading to its approval by the Food and Drug Administration for use in NSCLC in 2013." (PMID 28895885, 2017). "Translocation of anaplastic lymphoma kinase (ALK) gene is an important determinator for the response to ALK tyrosine kinase inhibitor (TKI) in non-small-cell lung cancer (NSCLC) patients." (PMID 28887531, 2017). "Patients with advanced stage non-small cell lung carcinoma (NSCLC) harboring an anaplastic lymphoma kinase ALK gene rearrangement, detected from a tissue sample, can benefit from targeted ALK inhibitor treatment." (PMID 28805673, 2017). "We developed an enzyme-linked immunosorbent assay (ELISA) to measure anti-ALK antibody levels and mapped specific peptide epitope sequences within the ALK cytoplasmic domain in patients with non-small cell lung cancer." (PMID 29190913, 2017). "Crizotinib is a class Ia small molecule dual inhibitor of c-Met and anaplastic lymphoma kinase (ALK) that was approved for therapeutic use in advanced non-small cell lung cancers positive for either c-ros oncogene 1 (ROS-1) or ALK." (PMID 29231907, 2017). "The anaplastic lymphoma kinase (ALK) protein has recently become a promising target in the treatment of non-small cell lung carcinomas(NSCLC) patients with ALK translocation because of the high response rates obtained with an ALK inhibitor." (PMID 29312572, 2017). "In 2007, Soda and colleagues concluded that the ALK gene fusion was also an oncogenic driver of non-small cell lung cancer (NSCLCs)." (PMID 28549458, 2017). "In 2007, scientists found that anaplastic lymphoma kinase (ALK) gene rearrangements are present in a small subset of non-small cell lung cancers." (PMID 29312572, 2017). "To address this, we evolved resistance in an ALK rearranged non-small cell lung cancer line (H3122) to a panel of 4 ALK TKIs, and performed a collateral sensitivity analysis." (PMID 28450729, 2017).
non-small cell lung carcinoma (continued). "The anaplastic lymphoma kinase tyrosine kinase inhibitors (ALK-TKIs) have been administered to patients with ALK-positive non-small cell lung cancer for a long period of time and show a promising response." (PMID 28606126, 2017). "For example, NCCN supports use of ceritinib (Zykadia), approved in 2014 for ALK+ non-small cell lung cancer, for soft tissue sarcoma and inflammatory myofibroblastic tumors with the ALK translocation." (PMID 28045970, 2017). "The anaplastic lymphoma kinase (ALK) gene is rearranged in approximately 5% of non-small-cell lung cancer (NSCLC) cases, leading to constitutive activation of the ALK tyrosine kinase domain and tumorigenesis." (PMID 28423535, 2017). "Crizotinib, an inhibitor of tyrosine receptor kinases, including ALK and CD117, has been found to be effective against inflammatory myofibroblastic tumor or non-small cell lung cancer with ALK rearrangement." (PMID 27974674, 2017). "With the discovery of anaplastic lymphoma kinase (ALK) rearrangements, small-molecule ALK tyrosine kinase inhibitors (TKIs) become the most active therapeutic areas of study in ALK-positive non-small-cell lung cancer (NSCLC) patients." (PMID 28606126, 2017). "Treatment of metastatic ALK-rearranged non-small cell lung cancer with ALK inhibitors leads to higher response rates and improved progression-free survival relative to conventional chemotherapy regimens." (PMID 28683775, 2017). "ALK gene copy number is frequently detected in clinical evaluation of solid tumors such as non-small cell lung cancer, neuroblastoma, esophageal cancer and HCC, and has been associated with a subgroup of high-risk neuroblastoma and HCC." (PMID 28430645, 2017). "The identification of anaplastic lymphoma kinase (ALK) rearrangements is found in approximately 5% of non-small-cell lung cancers (NSCLCs)." (PMID 28938646, 2017). "A clinically-relevant example of this phenomenon occurs in ALK-positive non-small cell lung cancer, where targeted therapies are used to inhibit the ALK-EML4 fusion protein." (PMID 28450729, 2017). "Among the genomic alterations present in non-small cell lung carcinoma (NSCLC) the ALK rearrangement is one that results in targeted therapy and in most cases gives a therapeutic response that prolongs the life of patients." (PMID 28805682, 2017). "Crizotinib is a first-in-class, orally available multi-targeted receptor tyrosine kinase (RTK) inhibitor for the treatment of anaplastic lymphoma kinase (ALK)-rearranged non-small cell lung cancer (NSCLC) that is locally advanced or metastatic." (PMID 28217366, 2017). "Among them, the first-generation ALK inhibitor crizotinib was approved by the US FDA in 2011 for the treatment of ALK(+) non-small-cell lung cancer." (PMID 28771164, 2017). "In non-small cell lung cancer it was shown that ALK rearrangements (that were previously thought to be mutually exclusive with activating EGFR and KRAS mutations) can be found together with EGFR mutations in rare cases." (PMID 28549417, 2017). "Crizotinib is the first tyrosine kinase inhibitor (TKI) successfully tested in ALCL patients and in 2011 it was approved for the treatment of ALK+ non-small cell lung cancer (NSCLC)." (PMID 27662658, 2016). "In non-small cell lung cancer (NSCLC), echinoderm microtubule-associated protein-like 4 (EML-4) and kinesin family member 5B (KIF5B) account for the majority of ALK gene rearrangement lung cancer." (PMID 26966027, 2016). "Anaplastic lymphoma kinase (ALK) gene rearrangement is detected in 3 % to 13 % of non-small cell lung carcinoma patients, and these patients benefit from ALK inhibitors." (PMID 27142166, 2016). "ALK status was introduced in routine practice in 2011 after it was recognized as a molecular target of crizotinib in non-small-cell lung cancer." (PMID 26968843, 2016). "EGFR, KRAS, and ALK alterations are major genetic changes found in non-small cell lung cancers (NSCLCs)." (PMID 26992209, 2016).
non-small cell lung carcinoma (continued). "A subset of Non-Small Cell Lung Carcinoma (NSCLC) carries chromosomal rearrangements involving the Anaplastic Lymphoma Kinase (ALK) gene." (PMID 27119231, 2016). "ALK-break positive non-small cell lung cancer (NSCLC) patients initially respond to crizotinib, but resistance occurs inevitably." (PMID 27045755, 2016). "It is well tolerated and has already received FDA approval for the treatment of patients with metastatic non-small cell lung cancer that are positive for activating ALK fusions." (PMID 27363027, 2016). "As a proof of principle, we assessed the feasibility of characterizing the anaplastic lymphoma receptor tyrosine kinase (ALK) gene rearrangement by FISH in CTCs isolated from patients with non-small cell lung carcinoma (NSCLC)." (PMID 27739521, 2016). "Te fusion between echinoderm microtubule-associated protein 4 (EML4) and anaplastic lymphatic tumor kinase (ALK) rearrangement is present in approximately 5% of non-small cell lung cancer (NSCLC) patients." (PMID 26805736, 2016). "The principal mutations of EGFR, ALK, KRAS, BRAF, PIK3CA and HER2 were analyzed in 44 patients with non-small-cell lung cancer." (PMID 26968843, 2016). "Anaplastic lymphoma kinase (ALK) gene rearrangement in non-small cell lung cancer (NSCLC) is routinely evaluated by fluorescent in-situ hybridization (FISH) testing on biopsy tissues." (PMID 26993609, 2016). "The first-in-class inhibitor of ALK, c-MET and ROS1, crizotinib (Xalkori), has shown remarkable clinical efficacy in treatment of ALK-positive non-small cell lung cancer." (PMID 27483357, 2016). "Previous case reports have described esophagitis thought to be secondary to crizotinib, an oral tyrosine-kinase inhibitor used in the treatment of anaplastic lymphoma kinase- (ALK-) positive non-small cell lung cancer (NSCLC)." (PMID 28053793, 2016). "A platinum-based combination chemotherapy is currently the standard first-line therapy for patients with advanced Epidermal Growth Factor Receptor (EGFR) gene and Anaplastic Lymphoma Kinase (ALK) gene wild-type non-small cell lung cancer (NSCLC)." (PMID 27064343, 2016). "Subsequently, in 2007, ALK was found fused to echinoderm microtubule associated protein-like 4 (EML4) yielding the fusion kinase EML4-ALK seen in approximately 3–5% of non-small cell lung cancers (NSCLC)." (PMID 27009859, 2016). "A small subset (3–13 %) of non-small cell lung cancer (NSCLC) has been shown to have rearrangements in the ALK (anaplastic lymphoma kinase) gene." (PMID 26951079, 2016). "The management of anaplastic lymphoma kinase rearranged (ALK+) non-small cell lung cancer (NSCLC) exemplifies the potential of a precision medicine approach to cancer care." (PMID 27965961, 2016). "ALK positivity, defined according to Ventana CDx guidelines, was identified in 16 tumors (2.0 %), including 12 adenocarcinomas, two non-small cell carcinoma NOS, and two squamous cell carcinomas." (PMID 27495736, 2016). "In this perspective study, we screened 364 patients with advanced non-small cell lung cancer (NSCLC) for ALK rearrangements, and collected blood samples from 24 of them with confirmed ALK rearrangements based on their tissue biopsies." (PMID 27564104, 2016). "For example, patients having EML4-ALK fusion in non-small-cell lung cancer (NSCLC) are highly responsive to the ALK inhibitor crizotinib and ceritinib." (PMID 27150058, 2016). "Crizotinib show a promising efficacy in patients with anaplastic lymphoma kinase (ALK)-positive non-small cell lung cancer (NSCLC)." (PMID 27835601, 2016). "Oscar Arrieta, principal investigator of CLICAP, Frequency of ALK Rearrangements in Non Small-Cell Lung Cancer in Latin America: The Latin-American Consortium for the Investigation of Lung Cancer (CLICaP)." (PMID 27191954, 2016). "Despite the impressive efficacy of crizotinib for the treatment of ALK-positive non-small cell lung cancer, patients invariably develop therapeutic resistance." (PMID 27144340, 2016).
non-small cell lung carcinoma (continued). "The aim of this study is to explore clinical efficacy of crizotinib in advanced anaplastic lymphoma kinase (ALK) positive non-small cell lung cancer." (PMID 26483333, 2015). "Recent studies showed that Crizotinib is also active against anaplastic lymphoma kinase (ALK) and has been approved for the treatment of locally advanced or metastatic non small cell lung cancer that is ALK-positive." (PMID 25909285, 2015). "We investigated the mechanism of acquired resistance to 17-(Dimethylaminoethylamino)-17-demethoxygeldanamycin (17-DMAG), a geldanamycin analogue Hsp90 inhibitor, in H3122 and H2228 non-small cell lung cancer cell lines with ALK rearrangement." (PMID 26219569, 2015). "Crizotinib is superior to standard chemotherapy in patients with previously treated, advanced ALK positive non-small cell lung cancer.The median PFS of patients is shorter.It can improve the quality of life about patients." (PMID 26483333, 2015). "Non-small-cell lung cancers (NSCLCs) harboring translocations in anaplastic lymphoma kinase (ALK) are highly sensitive to small-molecule ALK kinase inhibitors, such as crizotinib." (PMID 25899913, 2015). "Ceritinib (LDK378) is a second-generation tyrosine kinase inhibitor of anaplastic lymphoma kinase (ALK) currently in phase III clinical trial for the treatment of non-small cell lung cancer." (PMID 26556876, 2015). "The fusion between anaplastic lymphoma kinase (ALK) and echinoderm microtubule-associated protein-like 4 (EML4) is a causative factor in a unique subset of patients with non-small cell lung carcinoma (NSCLC)." (PMID 26517679, 2015). "Crizotinib is an oral small-molecule inhibitor of anaplastic lymphoma kinase (ALK) approved by US Food and Drug Administration (FDA) for the treatment of advanced non-small cell lung cancer (NSCLC) with ALK rearrangements." (PMID 26677850, 2015). "ALK inhibitors are the standard of care for ALK-rearranged non-small cell lung cancer, and the resulting success is the paradigm for precision oncology." (PMID 26062823, 2015). "Recently, echinoderm microtubule-associated protein-like 4 (EML4)-ALK fusion and vinculin (VCL)-ALK fusion have also been identified in non-small cell lung cancer (NSCLC) and renal cell carcinoma, respectively, which has not been described in IMT or EIMS yet." (PMID 26178751, 2015). "Rearrangement in the anaplastic lymphoma kinase (ALK) gene is one of the potent oncogenic drivers in patients (pts) with non-small cell lung cancer (NSCLC) and occurs in approximately 5 % of cases." (PMID 26342831, 2015). "Recently, the rearrangement of anaplastic lymphoma kinase (ALK) was detected in a small but significant proportion of patients with non-small cell lung cancer (NSCLC)." (PMID 26295973, 2015). "Crizotinib is an anaplastic lymphoma kinase (ALK) tyrosine kinase inhibitor used in treatment of metastatic ALK-positive non-small-cell lung cancer." (PMID 26421283, 2015). "EML4 is currently under intense investigation in non small cell lung cancer where it is frequently found fused to the ALK gene." (PMID 25993117, 2015). "Many drugs are being developed for defined molecular targets, one such example is the use of crizotinib in anaplastic lymphoma kinase (ALK) positive non-small cell lung cancer (NSCLC)." (PMID 24782887, 2014). "ALK expression has been found in several types of cancers, such as anaplastic large-cell lymphoma, non-small cell lung cancer, diffuse large B-cell lymphoma, and inflammatory myofibroblastic tumors." (PMID 25193856, 2014). "Most recently crizotinib was approved for use in non-small-cell lung carcinoma (NSCLC) patients as ALK inhibitor." (PMID 25054154, 2014). "In clinical trials, Crizotinib was approved by the US Food and Drug Administration (FDA) as a treatment for locally advanced or metastatic ALK-rearranged non-small cell lung cancer in 2011." (PMID 25193856, 2014).